DPYD (dihydropyrimidine dehydrogenase)
Description:
Involved in pyrimidine base degradation. Catalyzes the reduction of uracil and thymine. Also involved the degradation of the chemotherapeutic drug 5-fluorouracil.
Synonyms: DHPDHase; DPD; DHP; DYPD
Tractability: Small molecule: a drug acting on it is in phase 2 or 3 trials; it belongs to a druggable protein family. PROTAC: ubiquitination databases record sites on it; its protein half-life has been measured; a small molecule that binds it is known.
Target class: Enzyme; Oxidoreductase
Safety:
Unwanted effects reported when the protein is acted on. In parentheses: how it was acted on, where the effect was seen, and who reports it.
diarrhea (source: ClinPGx)
drug toxicity (source: ClinPGx)
hand-foot syndrome (source: ClinPGx)
hyperbilirubinemia (source: ClinPGx)
Gene: Protein-coding gene on chromosome 1 (97,077,743 to 97,995,000, reverse strand). Ensembl gene ENSG00000188641.
Subcellular location: Cytoplasm
Pathways (Reactome):
Metabolism: Pyrimidine catabolism
Gene Ontology:
Molecular function: dihydropyrimidine dehydrogenase (NADP+) activity; protein binding; protein homodimerization activity; flavin adenine dinucleotide binding; NADP binding; uracil binding; iron-sulfur cluster binding; oxidoreductase activity; oxidoreductase activity, acting on the CH-CH group of donors
Biological process: purine nucleobase catabolic process; pyrimidine nucleobase catabolic process; thymine catabolic process; TMP catabolic process; UMP catabolic process; uracil catabolic process; xenobiotic catabolic process; beta-alanine biosynthetic process; CMP catabolic process; dCMP catabolic process; dUMP catabolic process
Cellular component: cytosol; cytoplasm
Genetic constraint (gnomAD): Loss-of-function variants: 95 observed, 103.32 expected, observed/expected ratio (o/e) 0.92, 90% interval 0.78 to 1.09. The upper end of that interval is the gene's LOEUF score, 1.09, which puts it in group 4 of 6, group 1 being the genes least tolerant of losing a copy. Missense variants: 1,194 observed, 1,203.5 expected, observed/expected ratio (o/e) 0.99, 90% interval 0.94 to 1.04. Synonymous variants: 404 observed, 412.4 expected, observed/expected ratio (o/e) 0.98, 90% interval 0.9 to 1.06.
Homologues: Orthologues: chimpanzee DPYD (99% identical), macaque DPYD (97% identical), pig DPYD (93% identical), rabbit DPYD (93% identical), dog DPYD (92% identical), guinea pig DPYD (92% identical), mouse Dpyd (90% identical), rat Dpyd (90% identical), tropical clawed frog dpyd (82% identical), zebrafish dpydb (76% identical), Caenorhabditis elegans dpyd-1 (66% identical), Drosophila melanogaster su(r) (66% identical), and 1 more. Paralogues in human: DHODH (10% identical), FDXR (7% identical).
Diseases named in the same sentence as DPYD in open-access papers:
DPYD is named in the same sentence as 97 diseases in open-access papers, as found by Europe PMC text mining. Sharing a sentence is not in itself a finding about the gene and the disease. The quoted sentences say what the papers report.
colorectal cancer (35 papers, 1998 to 2026). A primary or metastatic malignant neoplasm that affects the colon or rectum. "In conclusion, DPYD variants were found in 7% of patients treated with fluoropyrimidine-based chemotherapy at our centre, with colorectal cancer patients showing the highest prevalence." (PMID 41562939, 2026). "The DPYD*4 CT genotype was associated with decreased catalytic activity of DPD, and an increased risk of drug toxicity when treated with capecitabine or fluorouracil in colorectal cancer patients, as compared to CC genotype." (PMID 39065653, 2024). "Indeed, in vitro studies have revealed that DPYD overexpression in cancer cell lines correlated with 5-FU resistance and high levels of DPYD mRNA expression in colorectal cancer have also been demonstrated to be linked with resistance to 5-FU." (PMID 36361992, 2022). "We show that high expression levels of DPYD is linked to poor outcomes in colorectal cancer." (PMID 28851987, 2017). "Likewise, high DPYD transcript level was associated with poor outcome of stage IV colorectal cancer patients." (PMID 27733154, 2016). "The aim of the present study is to elucidate the clinical role of the DPYD rs4294451 variant as predictive pharmacogenetic markers of the clinical outcome (severe toxicity and prognosis) related to an FL-based treatment in a cohort of 645 patients with colorectal cancer (CRC)." (PMID 39703399, 2024). "miR-27a-3p led to sensitization of colorectal cancer cells to the drug by diminishing the expression of dihydropyrimidine dehydrogenase (DPYD), responsible for converting administered 5-FU to the inactive metabolite." (PMID 31810268, 2019). "The aim of this study was to investigate the effect of dihydropyrimidine dehydrogenase (DPYD), thymidylate synthase (TYMS), and methylenetetrahydrofolate reductase (MTHFR) polymorphisms in colorectal cancer patients." (PMID 30551678, 2018). "Colorectal cancer patients with low protein expression of 5-FU inactivating enzyme dihydropyrimidine dehydrogenase (DPYD, OMIM: 612778) exhibited a longer survival after 5-FU-treatment than those with high levels." (PMID 27733154, 2016). "Two such biomarkers thymidylate synthase (TS) and dihydropyrimidine dehydrogenase (DPD) play key roles for response to 5-fluorouracil therapy of colorectal cancer." (PMID 19154585, 2009). "The association of MSI and MMR status with outcome and with thymidylate synthase (TS) and dihydropyrimidine dehydrogenase (DPD) expression in colorectal cancer were evaluated." (PMID 19154585, 2009). "The aim of this study was to evaluate the importance of serum dihydropyrimidine dehydrogenase (DPD) enzyme levels in Iraqi male individuals who have been diagnosed with colorectal cancer and are currently receiving fluoropyrimidine-based chemotherapy, specifically capecitabine." (PMID 37790008, 2023). "Since the expression of dihydropyrimidine dehydrogenase (DPD) is known to be lower in female colorectal cancer patients, it appears more likely that women might be more sensitive to 5-FU and its prodrug capecitabine." (PMID 35251955, 2022). "Analysis of the GSE14333 data-set42 in 226 colorectal cancer patients comprised mainly of Duke Stage B and C cancers revealed that high DPYD mRNA expression correlates with poor disease free survival as compared to those expressing low DPYD mRNA levels." (PMID 28851987, 2017).
colorectal cancer (continued). "We analyzed whether tumor DPYD mRNA expression could predict poor outcome in colorectal cancer patients treated with chemotherapy." (PMID 28851987, 2017). "Fifteen patients with colorectal cancer participated in semi-structured interviews, designed to get their opinions on the dissemination of information about dihydropyrimidine dehydrogenase (DPD) testing, that is done before delivery of treatment to reduce side effects." (PMID 39346592, 2024). "Dihydropyrimidine dehydrogenase (DPD) deficiency is a pharmacogenetic syndrome associated with life-threatening toxicity following exposure to the fluoropyrimidine drugs 5-fluorouracil (5-FU) and capecitabine (CAP), widely used for the treatment of colorectal cancer and other solid tumors." (PMID 23335937, 2012). "There are few studies on the DPYD, ARHGEF6, MCTP2 and SPN genes in AML, but these genes are known to be differentially expressed in other tumors, such as colorectal cancer, lung cancer and hepatocellular carcinoma." (PMID 36879313, 2023). "Preclinical data reported for a colorectal cancer cell line (SW480) demonstrated that miR-494, by interacting with the 3′UTR of the DPYD gene, negatively regulated endogenous DPYD expression." (PMID 35158962, 2022). "For instance, it has been suggested that females have lower expression of dihydropyrimidine dehydrogenase (DPD), i.e., the rate-limiting catabolic enzyme for 5-FU, in their colorectal carcinomas which make them more sensitive to 5-FU." (PMID 33099678, 2021). "An important anticancer agent widely used in the treatment of colorectal cancers, 5-fluorouracil (5-FU), is catabolised rapidly to the inactive metabolite dihydrofluorouracil (FUH2) by the first and rate-limiting enzyme-dihydropyrimidine dehydrogenase (DPD)." (PMID 14562021, 2003). "Furthermore, CEBPB signaling has been shown to be activated in colorectal cancer cells following treatment with 5-FU, suggesting that CEBPB-mediated activation of DPYD expression might represent a dynamic response to therapy." (PMID 38686795, 2024). "S1, an oral fluoropyrimidine composed of tegafur (a 5-FU prodrug), gimeracil (a dihydropyrimidine dehydrogenase, DPD, inhibitor), and potassium oxonate, is employed in Asia and in some European Countries for the treatment of different kinds of solid tumors, including advanced colorectal cancer." (PMID 36186986, 2022). "Similarly, the results of studies indicating potential prognostic role of DPYD or TYMP expression for survival of colorectal cancer patients after 5-FU-treatment were not replicated." (PMID 27733154, 2016).
breast carcinoma (16 papers, 2002 to 2025). "She had a known history of treatment for breast cancer, on chemotherapy, and was also diagnosed with dihydropyrimidine dehydrogenase (DPD) deficiency." (PMID 40443641, 2025). "Nevertheless, a study analyzing 33 germline polymorphisms in the 3′UTR of genes involved in drug absorption, distribution, metabolism and elimination (ADME) showed that DPYD rs291593 was associated with recurrence-free survival in breast cancer patients." (PMID 34442436, 2021). "Several in vitro and in vivo studies have revealed a strong association between increased TS and DPYD expression and the resistance to 5-FU in various tumors including breast cancer." (PMID 24040364, 2013). "To further confirm the potential role of TS and DPYD in 53BP1 mediated 5-Fu sensitivity in breast cancer cells, we used TS siRNA and DPYD siRNA to knockdown the levels of TS or DPYD in 53BP1 knockdown MCF-7 cells." (PMID 24040364, 2013). "In conclusion, dihydropyrimidine dehydrogenase is a possible prognostic factor in patients with breast cancer treated with 5-fluorouracil or 5-fluorouracil derivatives." (PMID 11870510, 2002). "We have investigated dihydropyrimidine dehydrogenase expression as a prognostic marker in breast cancer." (PMID 11870510, 2002). "Based on this background, we evaluated whether the mRNA expression of thymidylate synthase, thymidine phosphorylase, and DPYD was altered in the TAM-resistant breast cancer sublines." (PMID 34101751, 2021). "DPD (dihydropyrimidine dehydrogenase, encoded by DPYD gene) is the initial and rate-limiting enzyme of metabolic pathway of fluoropyrimidines, and fluoropyrimidines are common used drug therapies for breast cancer." (PMID 29340111, 2017). "Hence, it is not clear whether the decreased expression of DPYD mRNA is attributed to the characteristics of the breast cancer cell line itself or otherwise to the dose or duration of treatment with tamoxifen." (PMID 34101751, 2021).
gastric cancer (15 papers, 2004 to 2021). A primary or metastatic malignant neoplasm involving the stomach. "Another study revealed that gene polymorphisms of DPYD could be considered as a biomarker for prediction of gastric cancer patients survival treated with 5-fluorouracil-based adjuvant chemotherapy." (PMID 32695278, 2020). "Results from subset analysis of the FLAGS trial and JCOG9912 showed that S-1 was better than 5-FU in patients with gastric cancer associated with high dihydropyrimidine dehydrogenase (DPD), which was found more commonly in diffuse-type tumors than in intestinal-type tumors." (PMID 24392116, 2014). "Literature showed S-1 was better in patients with high dihydropyrimidine dehydrogenase, while capecitabine was reported to be more effective in high thymidine phosphorylase gastric cancer." (PMID 24349363, 2013). "The predictive values of thymidylate synthase (TS) and dihydropyrimidine dehydrogenase (DPD) gene expressions were retrospectively evaluated in patients with gastric cancer treated by a regimen containing S-1." (PMID 15354215, 2004). "The potential impact that the intratumoral expression level of dihydropyrimidine dehydrogenase (DPD) has on chemotherapy sensitivity and long-term survival for gastric cancer (GC) patients remains controversial; therefore, this study seeks to clarify this issue." (PMID 28255193, 2017). "For example, polymorphisms of rs1801159 in dihydropyrimidine dehydrogenase (DPD), a key enzyme involved in the catabolism of 5-fluorouracil (5-FU), may be utilized as valuable FU-based chemotherapy response predictors for patients with gastric cancer in the Chinese population." (PMID 25788990, 2015). "Dihydropyrimidine dehydrogenase (DPD) inhibitory fluoropyrimidine (DIF), the oral form prodrug of 5-flurouracil (5-FU), has been developed since 1980, and is currently the most important chemotherapeutic agent used in adjuvant chemotherapy for advanced gastric cancer." (PMID 33865416, 2021).
neutropenia (13 papers, 2014 to 2024). A decrease in the number of neutrophils found in the blood. "Patients with partial DPYD gene deficiency and subsequent impaired DPD activity were shown to have 3-4-fold higher risk of 5-FU-related neutropenia." (PMID 29507678, 2018). "More mutational alleles of UGT1A1*6/*28 and DPYD*5 were also revealed to had increased incidence of severe neutropenia (P = 0.008)." (PMID 28637434, 2017). "The ABCB1 rs17064 heterozygous variant (AT) (OR 4.56; 1.25–16.63; p = 0.021), DPYD rs291583 allele G (OR 1.83; 1.03–3.21; p = 0.036) and positive HER2 status (OR 1.69; 0.99–2.87; p = 0.049) increased overall neutropenia risk." (PMID 39596349, 2024). "In our group two independent predictors of severe neutropenia, variants in TYMS and DPYD genes, belong to 5-fluorouracil pathway." (PMID 29507678, 2018). "In contrast, non-functional variants in the DPYD gene were associated with the develop of severe ADRs such as neutropenia, nausea, severe diarrhoea, or hand-foot syndrome in fluoropyrimidine-treated patients." (PMID 37111771, 2023). "DPYD rs1801160 has not been associated straight forward with FP-induced toxicity in several studies, there are, however, reports showing that this variant allele may induce neutropenia risk." (PMID 37781702, 2023).
colon carcinoma (12 papers, 2002 to 2024). "Among these mRNAs, DPYD variants was reported to be a predictor of 5-fluorouracil toxicity in adjuvant colon cancer treatment." (PMID 31850052, 2019). "BRAF and DPYD mutations can be used as markers to guide treatment in colon cancer." (PMID 34594379, 2021). "Further pieces of evidence suggest that miR-494 sensitizes colon cancer to 5-FU by targeting dihydropyrimidine dehydrogenase (DPYD), an enzyme involved in β-alanine metabolism." (PMID 36013278, 2022). "In addition, dihydropyrimidine dehydrogenase (DPYD), a 5-FU metabolizing enzyme, has been correlated with clinical response to 5-FU-based chemotherapy among colon cancer patients." (PMID 23420099, 2013).
dihydropyrimidine dehydrogenase deficiency (9 papers, 2013 to 2025). Dihydropyrimidine dehydrogenase (DPD) deficiency isaconditionin which the body cannot break down the nucleotides thymine and uracil. "Dihydropyrimidine dehydrogenase deficiency screening included gene encoding DPD (DPYD) genotyping using complete genome sequencing and DPD phenotyping (uracilemia or dihydrouracilemia/uracilemia ratio) or both tests." (PMID 38523525, 2024). "Recent evidence ascribes to germline pathogenic variants in the DPYD gene a crucial role in the development of DPYD deficiency, leading to a reduction in DPYD activity." (PMID 38745766, 2024). "Genotype–phenotype correlations were investigated by performing DPYD exon sequencing in 94 patients assessed for DPD deficiency by the 5-FU degradation rate (5-FUDR) assay." (PMID 36430399, 2022). "Dihydropyrimidine dehydrogenase deficiency secondary to polymorphisms in the DPYD gene can lead to significant toxicity associated with the administration of fluoropyrimidine chemotherapy." (PMID 30898145, 2019). "The entire DPYD gene was sequenced, and the patient was found to be heterozygous for three different polymorphisms that have reportedly been associated with dihydropyrimidine dehydrogenase deficiency." (PMID 30898145, 2019). "Genetic polymorphism in the DPYD gene is the most well-recognized cause of DPD deficiency, with the clinically most relevant polymorphism being DPYD*2A." (PMID 30898145, 2019). "Variants within DPYD result in dihydropyrimidine dehydrogenase deficiency, an error in pyrimidine metabolism associated with thymine-uraciluria and an increased risk of toxicity in cancer patients receiving 5-fluorouracil chemotherapy." (PMID 24109560, 2013). "The study cohort was appositely selected to include most of the DPD deficiencies cases (N = 40) identified by previous phenotyping of about 1000 patients, with the aim to detect specific associations between rare or novel DPYD variants and decreased DPD activity." (PMID 36430399, 2022). "On the other hand, DPYD exon sequencing did not reveal a clear genetic determinant for more than a half of the analysed cases of DPD deficiency." (PMID 36430399, 2022).
esophageal cancer (8 papers, 2013 to 2025). A primary or metastatic malignant neoplasm involving the esophagus. "DPYD encodes dihydropyrimidine dehydrogenase, which has been associated with chemosensitization, esophageal cancer, and NADPH oxidation." (PMID 39919125, 2025). "The copy number of DPYD genes in the 5‐FU‐resistant TE‐5R esophageal cancer cell line was amplified compared to that in TE‐5 cells, and the mRNA and protein expression levels of DPYD in 5‐FU‐resistant cells was higher than that in wild‐type cells." (PMID 34766149, 2021). "In addition, tumor suppressor lncRNA LINC00261 could also reverse the chemoresistance to 5-FU in human esophageal cancer cells through regulating DNA methylation-dependent expression inhibition of dihydropyrimidine dehydrogenase (DYPD)." (PMID 34881242, 2021).